BMAL1 (basic helix-loop-helix ARNT like 1)
Diseases named in the same sentence as BMAL1 in open-access papers (continued):
Sharing a sentence is not in itself a finding about the gene and the disease.
fibrosis (6 papers, 2022 to 2025). the formation of excess fibrous connective tissue in an organ or tissue in a reparative or reactive process. "These published results agree with our data that show decreased REV-ERBα and increased BMAL1 expression in bleomycin-induced fibrosis." (PMID 36894533, 2023). "Finally, BMAL1 overexpression significantly resisted the effects of Ang II on oxidative stress, autophagy and, cardiac fibrosis in cardiomyocytes." (PMID 35996077, 2022). "However, given that BMAL1 is involved in fibrosis, our results, revealing differences in rhythm and clock-related gene expression levels between normal and scar fibroblasts, suggest a correlation between the peripheral circadian rhythm and skin disorders, warranting further investigation." (PMID 38396801, 2024).
myopia (6 papers, 2019 to 2025). "Refractive dysgenesis or myopia in mammals, particularly humans, necessitates future research to substantiate the role of Bmal1." (PMID 41243864, 2025). "They studied the effects of altering clock genes on eye development using different animal models, specifically observing mice with a deleted retinal-specific clock gene (Bmal1), which resulted in myopia and elongation of the vitreous chamber." (PMID 39045316, 2024). "Retinal-specific knockout of the clock gene Bmal1 in mice can induce a myopia shift and elongation of the vitreous chamber." (PMID 36313450, 2022). "In line with this evidence, it was reported that optical defocus alters the expression of several genes encoding endogenous eye clock and that targeted retina-specific disruption of the clock gene Bmal1 induces myopia-like phenotype in mice." (PMID 34107987, 2021). "In mice, retinal-specific knockout of the clock gene Bmal1 induces myopia and elongates the vitreous chamber, the optical compartment separating the lens and the retina." (PMID 31211778, 2019). "We find that the retinal-specific knockout of the clock gene Bmal1 induces relative myopia in mice, elongating both the overall axial length and the vitreous cavity of the eye, compared to the eyes of the Bmal1fl/fl control mice." (PMID 31211778, 2019). "A myopia mouse model was generated by disrupting the circadian clock gene Bmal1, as embodied by a significant increase in both axial length and vitreous chamber depth of Bmal1 knockout mice." (PMID 41243864, 2025). "In mice, Bmal1 clock gene knockout in retina produces myopia." (PMID 39028695, 2024). "We find that mice with a retinal specific knockout of Bmal1, a non-redundant component of the circadian clock, have myopia with a lengthened vitreous chamber, the optical compartment separating the lens and retina." (PMID 31211778, 2019).
nasopharyngeal carcinoma (6 papers, 2019 to 2024). A carcinoma arising from the nasopharyngeal epithelium. "The overexpression of Bmal1 in nasopharyngeal carcinoma cells (NPC) also allowed for similar conclusions." (PMID 37504857, 2023).
osteoporosis (6 papers, 2022 to 2026). A condition of reduced bone mass, with decreased cortical thickness and a decrease in the number and size of the trabeculae of cancellous bone (but normal chemical composition), resulting in increased fracture incidence. "Studies have reported that Bmal1 deficiency can lead to severe aging-related osteoporosis, and at 9 months of age, the loss of the Bmal1 gene leads to an approximate 50% weight loss." (PMID 38903177, 2024). "Using skeletal muscle-specific Bmal1 knockout mice, we observed osteoporosis-related phenotypes, including decreased bone mass and disrupted trabecular microarchitecture, along with disrupted diurnal expression of inflammatory cytokines." (PMID 42259765, 2026). "Our findings shed new light on the mechanism of BMSCs regulated by Bmal1 and suggest novel therapeutic targets for aging-related osteoporosis." (PMID 38150082, 2024). "Importantly, the osteoporosis-related phenotype resulting from muscle Bmal1 knockout or aging was alleviated by nighttime time-restricted feeding (TRF), which reestablished a feeding-driven diurnal variation in Hmox1 expression within the muscle and reduced serum IL-1α levels." (PMID 42259765, 2026). "Specifically, Bmal1 knockout in osteoblasts and bone marrow mesenchymal stem cells (BMSCs) activates osteoclasts and reduces bone mass, suggesting that the attenuation of bone tissue rhythms during aging may contribute to osteoporosis." (PMID 41404509, 2025).
alcohol use disorder (5 papers, 2013 to 2022). "Clinical investigations report reduced baseline Clock mRNA levels in patients with alcohol use disorder, as well reduced baseline mRNA levels of circadian proteins BMAL1, Per1, Per2, Cry1, and Cry2." (PMID 35456507, 2022).
amyloidosis (5 papers, 2020 to 2025). A disorder characterized by the localized or diffuse accumulation of amyloid protein in various anatomic sites. "Taken together, these results indicate that Bmal1 loss associated with a loss of circadian BAM function precipitates brain border amyloidosis." (PMID 41427288, 2025). "Moreover, in a mouse model of AD, Bmal1 regulated the expression of the APOE gene and Bmal1 deletion caused a loss of Aβ rhythms in the hippocampus, resulting in marked increases in the amyloid plaque burden." (PMID 33089205, 2020). "While we characterize one clock-controlled BAM function – engulfment – Bmal1 deletion in BAMs likely worsens amyloid pathology by dysregulating the timing of many cellular functions beyond engulfment, such as ECM maintenance." (PMID 41427288, 2025). "To understand how Bmal1-depleted astrocytes behave in the context of Aβ pathology, we examined astrocyte activation in the cortex of BMAL1 aKO mice crossed to the APP/PS1-21 model of Aβ-amyloidosis (Aldh1l1-CreERT2;Bmal1fl/fl;APP/PS1-21)." (PMID 35110643, 2022). "Interestingly, the inhibition of REV‐ERBs can increase the transcription of BMAL1 and enhance microglial Aβ phagocytic activity in AD animal models, which may be a strategy to clear and reduce the amyloid plaque deposition." (PMID 36056774, 2022). "Our study shows that the core clock protein Bmal1 was more highly expressed at ZT24 than at ZT12 in murine microglia and this was completely reversed in 5XFAD mice, suggesting microglial clock disruption in this amyloidosis model." (PMID 31800167, 2020).
autism (5 papers, 2017 to 2025). Persistent deficits in social interaction and communication and interaction as well as a markedly restricted repertoire of activity and interest as well as repetitive patterns of behavior. "Together, these results demonstrate that haploinsufficiency of Bmal1 can cause autism-like behavioral changes in mice, akin to those identified in Bmal1-null mice." (PMID 35682995, 2022). "In the present study, we demonstrated that the haploinsufficiency of Bmal1 can also cause a variety of autism-like phenotypes in mice, akin to those identified in Bmal1 KO mice." (PMID 35682995, 2022). "Here, we further investigated whether an incomplete loss of Bmal1 function could cause significant autism-like behavioral changes in mice." (PMID 35682995, 2022). "Our results demonstrate that heterozygous Bmal1 deletion led to a ~50–75% decrease in the levels of Bmal1 proteins in the brain and that the haploinsufficiency of Bmal1 is sufficient to cause significant autism-like phenotypes in mice." (PMID 35682995, 2022). "Autism-like behaviors, including altered vocalizations, deficits in socialization, and anxious behavior have now been identified in Bmal1+/- mice." (PMID 40720646, 2025). "In conclusion, the present study has advanced our previous work on Bmal1−/− mice and, further, indicates a key role for Bmal1 disruption in generating autism-like phenotypes in mice." (PMID 35682995, 2022). "Indeed, missense mutation of BMAL1 was found in ASD and haploinsufficiency of BMAL1 caused altered circadian rhythm and autism-like behavior in mice." (PMID 36860270, 2023). "Our recent study found that Bmal1-null mice exhibit a variety of autism-like phenotypes." (PMID 35682995, 2022). "We recently reported that global Bmal1 KO leads to autism-like behaviors in mice." (PMID 35682995, 2022). "The study, which focused on the association between autism and circadian genes in mice, demonstrated that mice lacking the Bmal1 gene exhibited differences in the expression of genes associated with autism and ataxia and also displayed dysregulated pathways, including overactive mTORC1 signaling." (PMID 37807632, 2023). "Using a conditional Bmal1 deletion in cerebellar PCs, most of the behavioral and molecular phenotypes seen in Bmal1 KO mice can be recapitulated, suggesting a significant role for Bmal1 expression in the cerebellum in generating autism-like phenotypes in Bmal1 KO mice." (PMID 35682995, 2022).
cardiomyopathy (5 papers, 2015 to 2025). A disease of the heart muscle or myocardium proper. "To circumvent cardiomyopathy associated with prolonged Bmal1 deletion, we generated an inducible cardiomyocyte-specific Bmal1 knockout mouse line (Bmal1loxP/loxP Myosin Cre+ mice) by crossing Bmal1 floxed (Bmal1loxP/loxP) mice with Myosin Cre+ mice." (PMID 38464103, 2024). "However, the role of BMAL1 in the development and prevention of cardiomyopathy was not well understood." (PMID 35996077, 2022).
chronic obstructive pulmonary disease (5 papers, 2018 to 2025). A chronic and progressive lung disorder characterized by the loss of elasticity of the bronchial tree and the air sacs, destruction of the air sacs wall, thickening of the bronchial wall, and mucous accumulation in the bronchial tree. "The expression levels of clock proteins such as BMAL1 and PER2 are reduced in inflamed lung tissue and peripheral blood mononuclear cells in patients with chronic obstructive pulmonary disease." (PMID 29534090, 2018). "The same study observed that the mRNA and protein levels of BMAL1, PER2, CRY1, and REV-ERBα were reduced in the peripheral blood mononuclear cells (PBMCs), lung tissue, and sputum cells of smokers and patients with chronic obstructive pulmonary disease (COPD) compared to non-smokers." (PMID 40255337, 2025).
cognitive decline (5 papers, 2022 to 2025). "Bmal1‐iKO‐associated cognitive decline is attributed to impaired adenosine signaling and compromised long‐term potentiation (LTP) in the hippocampus." (PMID 40539410, 2025). "In an AD mouse model, cognitive decline was associated with BMAL1/ARNTL deficiency, which promoted microglial-derived chronic inflammation through NF-κB activation." (PMID 38641847, 2024). "In addition to the loss of circadian rhythms, deletion of Bmal1 induces accelerated aging, cognitive decline, atrophy of skeletal muscle and other tissues, and a shortened lifespan in mice." (PMID 35437315, 2022). "Therefore, altered Bmal1 gene expression resulting from molar loss may have been associated with cognitive decline in this study." (PMID 37299434, 2023). "A decrease in BMAL1 expression is a signal for the differentiation of NPC and OPC, but more often it leads to neurodegenerative disorders, neurosignaling deficiency, cognitive decline, and various neurological and psychopathological disorders." (PMID 41440117, 2025). "We observed abrogation of cognitive decline by AAV‐A1R in Bmal1‐iKO mice." (PMID 40539410, 2025).
coronary artery disease (5 papers, 2015 to 2025). "A genome-wide analysis of single nucleotide polymorphisms in the human population revealed that BMAL1 was significantly associated with coronary artery disease." (PMID 40429770, 2025). "As the underlying mechanisms become further elucidated, BMAL1 may emerge as a critical therapeutic target for ischemic heart disease." (PMID 40429770, 2025). "Plaque remodeling in coronary artery disease was also recently shown to be influenced by BMAL1 activity." (PMID 35880253, 2022). "By integrating chronobiology with cardiology, BMAL1-centered interventions could redefine the management paradigm for ischemic heart disease, transforming chronobiological concepts from theoretical frameworks into clinical tools for personalized medicine." (PMID 40429770, 2025). "BMAL1 expression could be an aim for preventing and improving the prognosis of ischemic heart disease." (PMID 40429770, 2025). "In coronary artery disease, the ROS protective effects of active BMAL1 conveyed protection." (PMID 35880253, 2022).
gastric cancer (5 papers, 2019 to 2025). A primary or metastatic malignant neoplasm involving the stomach. "NR1D1 and NR1D2 are transcription factors that bind ROREs and act as transcriptional repressors to inhibit the expression of BMAL1:CLOCK, underlining the importance of considering circadian rhythms in gastric cancer development and treatment." (PMID 39062777, 2024). "As BMAL1 regulates inflammation, immune responses, expression of oncogenes and tumor suppressor genes, it may contribute to gastric cancer progression, development, and treatment." (PMID 37503323, 2023). "Metformin-based chronotherapy can disrupt BMAL1–CLOCK–PER1–HK2 axis, thereby affecting glycolysis oscillation to overcome trastuzumab resistance in HER2-positive advanced gastric cancer." (PMID 37503323, 2023). "The up-regulation of BMAL1, CLOCK, and PER in gastric cancer and the up-regulation of CRY1 in more advanced stage gastric cancer but not in the earlier stage has also been reported." (PMID 34966277, 2021).
inflammatory bowel disease (5 papers, 2022 to 2025). A spectrum of small and large bowel inflammatory diseases of unknown etiology. "Analysis of public datasets of human patients with inflammatory bowel disease (IBD) showed that BMAL1 was downregulated in IBD patients, suggesting a correlation between BMAL1 and IBD." (PMID 40307620, 2025). "Other studies showed that inflammatory bowel disease (IBD) patients exhibit suppressed CLOCK and BMAL1 expression in intestinal epithelial cells coupled to dysbiosis and aberrant immune activation." (PMID 41262263, 2025).
insomnia (5 papers, 2020 to 2025). A sleep disorder characterized by difficulty in falling asleep and/or remaining asleep. "Insomnia patients usually exhibit circadian rhythm disorders, and resveratrol can regulate the expression of biological clock genes BMAL1 and PER2 by activating SIRT1, thus adjusting the sleep–wake cycle and improving sleep quality." (PMID 40144750, 2025). "In healthy controls, insomnia severity correlated with evening expression of BMAL1, PER1, and CRY1." (PMID 39201748, 2024). "In particular, significant correlations were found between circadian properties of BMAL1 and PER2 with symptoms such as fatigue, insomnia, and nausea." (PMID 40382284, 2025). "However, a number of studies showed that the main clock genes (Bmal1, Clock, the Per family, Cry and others) function in various skin cells, and their work can be modulated by a number of additional factors (external light, UV light, feeding/insulin, sleep/insomnia etc.)." (PMID 37189753, 2023). "BMAL1 amplitude showed a strong negative correlation with insomnia in the rucaparib group (ρ = −0.748, 95% CI [−1, 0]; p = 0.05) and positive correlation in the rucaparib after the end of therapy (ρ = 0.314, 95% CI [−0.204, 0.705]; p = 0.33)." (PMID 40382284, 2025).
lipid metabolism disorders (5 papers, 2020 to 2025). "Cichoric acid suppresses lipid metabolic disorders by modulating BMAL1 in HepG2 cells." (PMID 33381029, 2020). "With age increased, Egr-1 rhythm alteration might result in the uncoupling of Egr-1 with both circadian genes BMAL1/CLOCK and lipid metabolic genes Cidea, which results in the decoupling of liver circadian and lipid metabolic disorders in ageing mice." (PMID 36964140, 2023). "However, whether the circadian clock genes Bmal1 and Clock are involved in the protective effect of PIP against lipid metabolism disorders remains unknown." (PMID 35628429, 2022).
metastatic melanoma (5 papers, 2018 to 2023). A melanoma that has spread from its primary site to another anatomic site. "Overall, we demonstrated that, in metastatic melanoma, a high bulk BMAL1 expression seems to be associated with a “too tumorigenic” program and could be a marker for immunotherapy response." (PMID 29946530, 2018). "Recent studies on metastatic melanoma have shown that a high level of BMAL1 is manifested by an increased T cell infiltration level." (PMID 37373286, 2023). "According to a recent study, in metastatic melanoma, high BMAL1 levels are related to enhanced T cell infiltration and activation." (PMID 35326729, 2022). "In metastatic melanomas, the expression of BMAL1 is responsible for T-cell activation, differentiation and exhaustion markers, CTLA-4, PD-1, and PD-L1." (PMID 35326729, 2022). "For example, higher BMAL1 expression is positively correlated with greater TMB in metastatic melanoma." (PMID 33794967, 2021). "In fact, in metastatic melanomas, BMAL1 expression exhibited a strong positive correlation with the expression of dendritic cell markers, T-cell markers CD4 and CD8A, and T-cell activation/differentiation markers." (PMID 29946530, 2018). "Within this line, our data revealed the potential of BMAL1 as a clinically relevant biomarker for immunotherapy response and overall survival of patients with metastatic melanoma." (PMID 29946530, 2018). "Interestingly, in metastatic melanomas, BMAL1 expression positively correlated with the number of total somatic mutations and predicted neoantigens." (PMID 29946530, 2018). "Additionally, the prognostic value of BMAL1 expression in metastatic melanomas was confirmed in two other independent datasets (GSE6590 and GSE54467)." (PMID 29946530, 2018). "Similarly, higher BMAL1 expression is positively correlated with greater TMB and increased antigen presentation, but not MMR pathway activation in metastatic melanoma." (PMID 33794967, 2021).
multiple sclerosis (5 papers, 2018 to 2025). A progressive autoimmune disorder affecting the central nervous system resulting in demyelination. "Of note, enhanced risk of multiple sclerosis has been associated with variations in the circadian genes ARNTL/BMAL1 and CLOCK, likely due to the regulatory role of the ARNTL gene in oligodendrogenesis." (PMID 36299487, 2022). "Deletion of Bmal1 in either lymphocytes or myeloid cells has also been shown to also reduce disease severity in the experimental autoimmune encephalomyelitis (EAE) model of multiple sclerosis." (PMID 38032732, 2024). "Indeed, circadian dysregulation has been associated with myelination disorders in the central nervous system, i.e. enhanced risk of multiple sclerosis correlated with mutations in ARNTL/BMAL1 and CLOCK circadian genes, owing to the regulatory role of the ARNTL gene in oligodendrogenesis." (PMID 36299487, 2022). "Since BMAL1 is important for OPC, BMAL1-KO, which is specific for this type of cell during neurodevelopment, leads to myelin thinning, dysregulation of cognitive and motor functions in mice, and sleep fragmentation, which is related to multiple sclerosis (Table A1)." (PMID 41440117, 2025).
pleural mesothelioma (5 papers, 2017 to 2022). A neoplasm that arises from the mesothelial cells of the pleura. "Bmal1 upregulation is found in certain types of pleural mesothelioma while Bmal1 knockdown is associated with reduced cell growth and induced apoptosis." (PMID 31311204, 2019). "Alternatively, BMAL1 knockdown was found to suppress proliferation, and anchorage-dependent and independent clonal growth of malignant pleural mesothelioma cells." (PMID 30375470, 2018). "BMAL1 was found to be upregulated in certain types of pleural mesothelioma, and subsequent experiments revealed reduced cell growth and induced apoptosis upon Bmal1 knockdown in tumorigenic cells, but not in cells derived from healthy tissue." (PMID 28425940, 2017).